IL6 (interleukin 6)
Diseases named in the same sentence as IL6 in open-access papers (continued):
Sharing a sentence is not in itself a finding about the gene and the disease.
Sepsis (continued). "Another study assessed the clinical significance of IL-6, PTX-3, and PCT in patients with sepsis and septic shock." (PMID 39201697, 2024). "Resistin had a distinct connection with the severity of the illness, as shown by APACHE II and SOFA scores, and showed a correlation with well-established indicators of cytokines, such as IL-6, IL-8, IL-10, TNF-α, and sepsis." (PMID 38562275, 2024). "Namely, it prevents the apoptosis of Purkinje cells by lowering the levels of pro-inflammatory cytokines (IL-6, TNF-α, IL-1β) that are elevated during sepsis and thus prevents sepsis-induced apoptosis in the brain." (PMID 39204155, 2024). "The determination of CRP and procalcitonin (PCT) is higher in the sepsis group compared with patients with ACLF; the serum concentrations of IL-6 and IL-10 are higher in severe sepsis and different from those in subjects with ACLF or with stable cirrhosis." (PMID 39337069, 2024). "This systemic inflammation, often observed in conditions such as sepsis, is characterized by elevated levels of inflammatory markers like C-reactive protein (CRP), interleukin-6 (IL-6), and tumor necrosis factor-alpha (TNF-α)." (PMID 39563441, 2024). "IL-6 and PCT are effective predictive biomarkers for 28-day mortality in patients with sepsis and septic shock initially admitted to the ED." (PMID 39407738, 2024). "Administration of anti-PD-L1 antibodies prevented sepsis-induced monocyte dysfunction and decreased TNF-α, IL-6, and IL-10 production at different stages of sepsis, implying an overall reduction in systemic inflammation." (PMID 37776443, 2024). "In a murine model of polymicrobial sepsis, the exogenous administration of an anticoagulant antibody that selectively blocks FXI activation by FXII led to reduced IL-6 and TNF-a, reduced PLT consumption, and improved overall survival." (PMID 39337090, 2024). "B1a cells are able to secrete IgM as well as immunomodulatory cytokines like IL-10, spontaneously or after infection, and GM-CSF, IL-6, IL-3, TNF; therefore, there is evidence that B1a cells play a protective role in sepsis and survival benefits." (PMID 38474403, 2024). "These patients can experience an impaired B-cell responsiveness induced by IL-6 and TNF-α, similar to that seen during sepsis." (PMID 38261584, 2024). "Other studies carried out on patients with sepsis or multiple inflammatory and respiratory problems have shown a reduction of CRP and IL-6 concentrations after n-3 FA supplementation." (PMID 38702342, 2024). "The specific objectives include determining which marker—IL-6, CRP, PCT or lactic acid—is most effective for predicting the prognosis of sepsis." (PMID 39589972, 2024). "During past decades, more than 200 biomarkers of sepsis such as procalcitonin (PCT), IL-6, H2S, and SP have emerged." (PMID 39769181, 2024). "In a mouse model of sepsis, this substance inhibited the production of TNF-α and IL-6 in peritoneal macrophages in a dose-dependent manner by inhibiting the expression of Toll-like receptor 2 (TLR2) and suppressing the activation of NF-κB." (PMID 39057789, 2024). "Combining the sensitive IL-6 (cut-off of 30 pg/mL) with the more specific CRP, sensitivity and specificity for sepsis prediction improved to 100% and 96%." (PMID 38671704, 2024). "In a CLP surgery-induced sepsis model of mice, the administration of 5–20 g/kg of the QX1 decoction reduced sepsis-induced upregulated levels of serum IFN-γ, IL-1β, IL-3, IL-6, IL-17, IL-4, IL-10 and TNF-α." (PMID 39051370, 2024). "Discussion: Therefore, our findings demonstrated that LBT effectively inhibits the production of inflammatory cytokines (IL-6, TNF-α, and IL-1β) and mitigates sepsis induced by LPS through modulating macrophages' ability to generate these cytokines." (PMID 38799158, 2024). "In accordance with the literature, our study indicated that the biomarkers IL6 and NLR correlated with a poor prognosis of sepsis." (PMID 38765257, 2024).
Sepsis (continued). "The deletion of the ferritin H-chain has demonstrated a mitigating effect on the inflammatory burden in a sepsis model, leading to reductions in interferon-γ (IFN-γ), interleukin-6 (IL-6), IL-1β, and IL-12." (PMID 39275069, 2024). "For cytokine profiles, the levels of both proinflammatory (such as IL-6, GM-CSF, and CXCL10) and anti-inflammatory (such as IL-1ra, IL-10, and PD-L1) cytokines were increased in bacteremia and sepsis patients compared to HCs." (PMID 38707899, 2024). "In the four studies analyzing a combination of IL-6 and CRP at sepsis suspicion, cut-off values ranged from 21.7 to 60 pg/mL and 4.05 to 14 mg/L, respectively, sensitivities ranged between 78.12 and 100% and specificities between 41 and 96%." (PMID 38671704, 2024). "In animal studies, acute sepsis increased S100A12 expression in serum and atrial tissues, correlating positively with inflammatory markers (IL-1β, IL-6, TNF-α) and negatively with heart rate, indicating a predisposition to AF." (PMID 39444551, 2024). "In our study, taraxerone inhibited sepsis-induced increases in inflammatory cytokines like TNF-α, IL-1β, and IL-6." (PMID 39543653, 2024). "Significant elevations in serum cytokines, such as IL-1β, IL-6, TNF-α, IL-8, and the IL-7 family of cytokines, have been noted during sepsis." (PMID 39201339, 2024). "ELISA results revealed that, compared to the normal group, the protein levels of TNF-α, IL-6, IL-10, and MCP-1 were increased in the sepsis model (P < 0.05)." (PMID 38961068, 2024). "In our study, it was observed that HCQ treatment drastically decreased the levels of IL-6 and TNF-α in sepsis-induced rats." (PMID 39596976, 2024). "A study evaluated the clinical utility of IL-6, PTX3, and PCT in patients with sepsis and septic shock by measuring the serum concentration of these markers in 142 subjects." (PMID 39201697, 2024). "To evaluate the effect of prematurity on the production of TNF-α and IL-6, we exposed preterm neonatal, term neonatal and adult WB to TLR ligands and sepsis-related bacteria." (PMID 38562936, 2024). "In this study, our findings demonstrated that LBT Lobetyolin effectively protects mice from sepsis induced by LPS by downregulating the production of pro-inflammatory cytokines such as TNF-α, IL-6, and IL-1β in macrophages." (PMID 38799158, 2024). "In this study, we will provide a detailed analysis of the production of IL-6 and TNF-α by preterm and term newborns at birth in response to different stimuli, such as various sepsis-related bacteria and TLR ligands." (PMID 38562936, 2024). "The protease inhibitor ulinastatin can reduce the expression of the proinflammatory factors IL-6, IL-8, and TNF-α, thereby improving the severity of sepsis in the urinary system in elderly individuals." (PMID 38674153, 2024). "We found that shared biological pathways, especially checkpoint, cytolytic activity, IL6/JAK/STAT3 signaling, and TLR pathway were significantly correlated with most of the infiltrating immune cells in sepsis and trauma." (PMID 38384415, 2024). "A recent meta-analysis has shown that the levels of IL-6 and TNF-α are valuable prognostic indicators for patients with sepsis in the intensive care unit." (PMID 39200283, 2024). "The concentrations of IL-1β (p < 0.001), IL-6 (p < 0.001), and TNF-α (p < 0.001) were significantly elevated in the liver in the Tac1+/+ mice following CLP-surgery-induced sepsis compared with the sham-operated controls." (PMID 38539834, 2024). "The high sensitivity and specificity of IL-6 at 24 hours post-trauma make it a valuable biomarker for the early detection of trauma-related complications like inapparent hypoxia, FES, sepsis, and MODS." (PMID 39371766, 2024). "Patients with a complicated post-operative course, with infection or sepsis, showed higher PCT and IL6 levels than patients with an uncomplicated course." (PMID 39274267, 2024).
Sepsis (continued). "A concentration-dependent production of TNF-α and IL-6 was observed after exposure of term neonatal or adult WB to different TLR ligands and sepsis-related bacteria." (PMID 38562936, 2024). "Other biomarkers that have been used in the diagnosis of sepsis are c-reactive protein (CRP), procalcitonin (PCT), and interleukin-6 (IL-6)." (PMID 38396935, 2024). "HMGB1 has been known to induce the production of cytokines like TNF-α, IL-1β, and IL-6 through various mechanisms, including the NF-κB and ERK 1/2 pathways, exacerbating the pathological condition of sepsis." (PMID 38474222, 2024). "For instance, IL‐6, complement C1q, and the SIC score are deemed to possess predictive value for early warning and prognosis in sepsis, and future research is warranted to further validate the clinical application value of these biomarkers." (PMID 39445002, 2024). "When compared to sham-operated mice (sham+vehicle), mice subjected to CLP-sepsis and treated with vehicle (CLP+vehicle) showed a significant increase in the serum levels of pro-inflammatory cytokines IL-1β, IL-6 and anti-inflammatory cytokine IL-10 (P<0.0001)." (PMID 39559354, 2024). "As expected, IL-4, IL-6, IL-10, IL-17, TNF-α, and CCL2 were significantly elevated from the early stage of sepsis, but on CLP day 6, all cytokines were reduced to levels similar to those of sham mice." (PMID 38385073, 2024). "Sepsis induces an up-regulation in the production of proinflammatory cytokines, including IL1-β, IL-6, and TNF-α." (PMID 38629103, 2024). "As the severity of sepsis escalated, levels of CD3+, CD4+, and CD4+/CD8+ correspondingly diminished in the 3 patient groups, while IL-6 and PCT levels exhibited a positive correlation with sepsis severity." (PMID 39465765, 2024). "Five of the eleven biomarkers (IL-6, TNF-α, IL-8, IL-10, and sST-2) were significantly higher in patients with GN sepsis or NEC than those with NS, CS, and GP sepsis (p < 0.05)." (PMID 38312920, 2024). "Several protein biomarkers have already been proposed as prognostic markers of sepsis, such as CRP, lipopolysaccharide binding protein, PCT, or cytokines such as tumor necrosis factor-α and interleukin-6." (PMID 39335614, 2024). "Our data suggest that HNF4α is required for a proper IL6-mediated APR, which appears to be diminished during sepsis despite elevated plasma IL6 levels." (PMID 39261648, 2024). "As expected, sepsis promoted a significant increase in PELF TNFα (4-fold) and IL-6 (5.1-fold) production." (PMID 39065714, 2024). "Epalrestat, a commercial ARI, was employed as an intervention in a rat sepsis model, demonstrating significant reductions in inflammatory factors TNF-α, IL-1β and IL-6." (PMID 38188141, 2024). "This intervention resulted in reduced levels of biochemical organ injury markers and inflammatory cytokines (IL-6, IL-10, and TNF-α), indicating attenuation of the sepsis-induced inflammatory response." (PMID 38888975, 2024). "In sepsis, the endothelium is activated directly by PAMPs or indirectly by NETs and pro-inflammatory cytokines, including TNF-α, IL-6, and IL-1." (PMID 37569751, 2023). "β-blockers can down-regulate inflammatory mediators (e.g., TNF-α, IL-6, HMGB-1) in animal models of sepsis to reduce the inflammatory response as well as inhibit cardiomyocyte apoptosis." (PMID 37964887, 2023). "Antiapoptotic activity, better modulation of macrophage function, reduction of pro-inflammatory mediators such as Interleukin 6 (IL-6) and tumor necrosis factor α (TNF-α), and inhibition of the inflammatory reaction to sepsis have also been reported." (PMID 37109010, 2023). "The mice 12 h after CLP-induced sepsis had marked elevations in TNF-α, IL-6, and INF-γ levels in serum." (PMID 37372931, 2023). "After the body suffers from burns, macrophages are overactivated into proinflammatory (M1) macrophages in the early stage of sepsis, which release inflammatory factors (IL1, IL6 and TNF‐α)." (PMID 37060578, 2023).
Sepsis (continued). "The intraperitoneal injection of PRE-084 mitigated sepsis-induced ALI, as evidenced by a decrease in ICAM-1, IL-6 levels, lung PMN infiltration, and lung vascular leakage." (PMID 38201208, 2023). "While IL-6, PIGF, and CRP were also significantly elevated in post-Sepsis patients compared to controls, the observed differences in TNFα, Tie-2, Flt-1, IL-7 and bFGF were unique to the post-COVID group." (PMID 36844209, 2023). "Elevated levels of TLR2 in multiple organs of old mice augment the expression of cardiodepressant cytokines TNF-α, IL-1β, IL-6 and MCP-1 during sepsis, leading to greater cardiac dysfunction and high mortality." (PMID 38094127, 2023). "Previous studies indicates that exacerbated production of inflammatory mediators, including IL-6 and MCP-1 in the myocardium, plays a mechanistic role in cardiac dysfunction induced by endotoxemia or sepsis." (PMID 38094127, 2023). "Coagulation, complement, IL6–JAK–STAT3 signaling, inflammatory response and TNFα signaling via NFκB were considerably enriched in the patients with pediatric sepsis (P adjusted < 0.05)." (PMID 37115484, 2023). "Numerous studies have also shown that excessive release of pro-inflammatory cytokines, such as IL-1β, IL-6 and TNF-α, triggers pathophysiological abnormalities in sepsis and plays an important role in septic lung injury." (PMID 36737780, 2023). "The traditionally used markers of infection and sepsis include C-reactive protein (CRP), interleukin-6 (IL-6) and procalcitonin (PCT)." (PMID 37876167, 2023). "miR‐126‐5p expression was negatively correlated with IL‐6, CRP, and PCT but positively correlated with IgA, IgM, and IgG as well as CD3+, CD4+, and CD8+ in patients with sepsis‐induced ALI." (PMID 37248197, 2023). "Instead, we demonstrate that increased IL-6 signalling, which is known to alter infection risk, could confound associations with reduced HDL particle count, and suggest this may explain part of the observed association between (small) HDL particle count and sepsis." (PMID 37814277, 2023). "Inflammatory markers as IL-6, IL-10 and procalcitonin have a predictive value only in HCMV seropositive patients in sepsis." (PMID 37907989, 2023). "During liver failure in an experimental model of sepsis in rats, glucose metabolism is disturbed, transaminase activity increases, and levels of IL-1β, TNF-α, and IL-6 increase." (PMID 38203627, 2023). "In the model of CLP sepsis, CTX significantly downregulated the expression of pro-inflammatory cytokines TNF-α and IL-6, and increased the ratio of lipoxin A4, prostaglandin E2, and IFN-γ in mice plasma." (PMID 37629199, 2023). "In this investigation, the sepsis group considerably outperformed the sham group in terms of blood levels of TNF-, TNF- receptor, and IL-6 (P<0.05)." (PMID 36937479, 2023). "Peripheral blood T lymphocyte subsets and serum IL-6, PCT are abnormally expressed in patients with sepsis, and have a close bearing on the severity of the disease, which has a certain predictive value for patients after recovery." (PMID 36694784, 2023). "Compared to the sham group, the sepsis group had significantly elevated levels of TLR-4, IL-6, TNF-α, MIF, F2-isoprostane, caspase-3, cTn-I, and CK-MB (p<0.05)." (PMID 37900081, 2023). "Recently, several serum (or plasma) biomarkers have been proposed for the timely diagnosis and prognostications of patients with sepsis, including C-reactive protein (CRP), procalcitonin (PCT), presepsin, and interleukin 6 (IL-6)." (PMID 37324133, 2023). "Our results showed that inhibition of PRMT1 downregulates the expression of COX‐2, IL‐6, sIL‐6, and p‐STAT3 in the kidney, which was induced by sepsis, revealing the regulation role of PRMT1 in inflammation and the IL‐6 trans‐signaling pathway." (PMID 37525933, 2023).
Sepsis (continued). "In agreement, another study reported an inverse relationship between the plasma levels of IL-6, MMP-8 and CXCL9 (indicative of systemic inflammation) and the TNF production capacity of whole blood obtained from patients with sepsis." (PMID 37415223, 2023). "In patients with culture-confirmed sepsis on DOL 1, serum IL-6 starts high from its peak and declines until 48 h of life while CRP starts increased but needs up to 48 h to reach its peak." (PMID 36216867, 2023). "CLP-induced experimental sepsis resulted in a significant upregulation in the expression levels of TNF-α, IL-1β, IL-6, IL-10, ROS and MDA." (PMID 36608000, 2023). "Our results showed that genes such as IFN-γ, TNF-α, IL-6, MIP-2, IL-10, KC (CXCL1), CCL-2, MPO, MMP9, TLR2, and LCN2 were significantly upregulated in the lungs of sepsis-induced ARDS mice compared to control mice." (PMID 37822934, 2023). "In an LPS-induced rat sepsis model, levels of degraded components from EGCX correlated closely with plasma TNF-α, IL-6, and coagulation biomarkers, whereas administration of unfractionated heparin (UFH) substantially alleviated EGCX injury and coagulopathy." (PMID 37350963, 2023). "They compared the plasma concentration of IL-6 between critically ill children with MIS-C and sepsis, noting that the concentration of IL-6 rose much more in patients with sepsis than in patients with MIS-C." (PMID 37676491, 2023). "During sepsis, immune cell-derived cytokines such as TNF-α, IL-IL-1-β, IL-6, and IL-10 activate the HPA axis." (PMID 37600769, 2023). "Finally, recent studies have shown that IL-6 could be used to define the etiology of sepsis." (PMID 37627653, 2023). "In sepsis patients’ whole blood assays, the blockers significantly decreased supernatant concentrations of TNF and IL-6 in response to added heat-killed E. coli and S. aureus, and of IL-1β in response to S. aureus." (PMID 37869001, 2023). "The serum levels of pro-inflammatory cytokines IL-1β, IL-6, and TNF-α were significantly increased after sepsis, and down-regulated by inhibiting MAPK14 to 56.7%, 64.8%, and 72.6% compared with the sepsis group, respectively." (PMID 37180171, 2023). "In contrast, LPS increased the supernatant IL-1β, IL-6, IL-8, IL-10, and TNF-α concentrations at 24 and 48 h better in patients with trauma than sepsis." (PMID 36615909, 2023). "Peripheral blood T lymphocyte subsets and serum IL-6, PCT are abnormally expressed in patients with sepsis, and have a close bearing on the severity of the disease." (PMID 36694784, 2023). "We have previously shown that A2BR-deficient mice have higher mortality and increased pro-inflammatory cytokines such as IL-6, TNF-α and MIP-2 in sepsis." (PMID 37438813, 2023). "In sepsis-induced AKI, high IL-1β, IL-6, TNF-α, and cell fragments negatively affect renal tubular epithelial cells." (PMID 36632449, 2023). "We collected clinical data and looked at inflammatory markers such as CRP and IL-6 and cardiac markers such as troponin T. We also reported the incidence of ARDS, sepsis, and death of each patient, and compared the 2 groups." (PMID 37662725, 2023). "In the rat model of CLP-induced sepsis, EA at ST36 significantly reduced the plasma NSE level and the expression of proinflammatory cytokines in brain tissue, such as TNF-α and IL-6, reducing brain damage." (PMID 37753078, 2023). "In our cohorts, NS patients showed statistically significant higher levels of inflammation, coagulation, and sepsis markers (such as NLR, CRP, ferritin, IL-6, TNF-α, D-dimer, fibrinogen, PCT, and LDH) compared to S patients." (PMID 36781931, 2023). "In this study, we found that betaine given by ip injection in the sepsis group decreased the levels of pro-inflammatory cytokines (TNF-α, CRP, IL 1-β, IL-6) and oxidative stress biomarkers (MDA, LA) and increased PaO2." (PMID 37970921, 2023). "These investigators also found septicemia 3 h after LPS injection, with a slight blood pressure drop, FHR increase, mild hypoxia, and IL-6 rise." (PMID 38032884, 2023).